AGR2 (anterior gradient 2, protein disulphide isomerase family member)
Diseases named in the same sentence as AGR2 in open-access papers (continued):
Sharing a sentence is not in itself a finding about the gene and the disease.
cancer (continued). "The potential of these 4 molecules as a novel drug target also has been shown in a variety of studies: An accumulated knowledge on AGR2, PDE4D, NINJ2 and CDC25B have accelerated the drug discovery targeting these molecules in the other cancers." (PMID 35841085, 2022). "AGR2, a member of the protein disulfide isomerase (PDI) family of endoplasmic reticulum (ER) proteins, regulates the growth and metastasis of malignant tumors." (PMID 34632938, 2021). "In a number of cancer cell models, AGR alters cell adhesion suggesting that AGR2 carries out ER-independent function(s)." (PMID 33717413, 2021). "EOC represents a clinical model for evaluating the cooperative or antagonistic role of AGR2 and AGR3 in cancer and in drug resistance." (PMID 34452625, 2021). "Therefore, AGR2 may be a useful biomarker for diagnosis and prognosis of the cancers." (PMID 33413231, 2021). "We used the CBioPortal database to analyze the mutual relation linking AGR2 and E-cadherin (CDH1) in cancer cell lines listed in the Cancer Cell Line Encyclopedia (CCLE)." (PMID 32570918, 2020). "In pancreatic intraepithelial neoplasia, AGR2 acts as a SMAD4-suppressible gene that regulates MUC1 levels and stimulates the initiation and progression of cancer." (PMID 32322663, 2020). "Anterior gradient 2 (AGR2), a protein belonging to the protein disulfide isomerase (PDI) family, is overexpressed in multiple cancers and promotes angiogenesis to drive cancer progression." (PMID 30647455, 2019). "Taken together, the role of AGR2 in EMT is dependent on its localization, which seems to be responsible for a set of different impacts on cancer cell migration, invasiveness and metastasis development." (PMID 28810836, 2017). "Previous publications have shown that the degree of immunohistochemical staining of carcinoma cells for the proteins described, OPN, S100A4, S100P, AGR2 and FANCD2, reflect the level of each particular protein in the specimens." (PMID 27100728, 2016). "Knockdown of AGR2 expression with an AGR2-specific short hairpin RNA (shRNA) in SNU-478, an ampulla of Vater cancer cell line resulted in decreased cell viability and in decreased anchorage-independent growth by 98%." (PMID 25367337, 2014). "In terms of distinguishing PDAC from benign disease and PDAC from other cancers, aside from CA19.9, AGR2 showed the best discrimination between these two groups." (PMID 24007603, 2013). "Why ERp44, AGR2, or AGR3 are essential for specific cancer cell lines is unclear but may relate to their unique biological and biochemical functions." (PMID 40867591, 2025). "Overall, immunotherapy targeting AGR2 expression in cancer is still in the preliminary stages and has not yet been incorporated into clinical practice." (PMID 39062458, 2024). "Taken together, our results suggest that PDK1 and AGR2 are regulated by different mechanisms or that the mechanisms described for AGR2 in cancer cells do not exist in L6 myotubes." (PMID 39080182, 2024). "Moreover, AGR2 triggers the UPR through its specific ER function, thereby promoting cancer progression via the UPR pathway." (PMID 39062458, 2024). "AGR2 would not be the first ER-resident protein lacking a transmembrane domain to be found on the cell surface of cancer cells." (PMID 39727484, 2024). "It appears from our explorations that AGR2 and AGR3 are connected to the cancer phenotype." (PMID 35857928, 2022). "As a general feature, the expression of epithelial genes (e.g. TJP3, TSPAN13, CLDN7 and EPCAM) was positively correlated with the expression of AGR2/3 and the expression of mesenchymal genes (e.g. VIM and MSN) was negatively correlated, with specific correlations according to cancer type." (PMID 35857928, 2022). "AGR2, an endoplasmic reticulum (ER)-resident protein disulfide isomerase (PDI), has been generating a massive interest because of its overexpression and vital roles in various cancers." (PMID 35841085, 2022).
cancer (continued). "Genes with no significant expression in the majority of the normal donors and exhibiting expression patterns associated with a particular cancer type were 16, among them AGR2, S100A14, S100A16, and FABP1 identified as those with the highest discrimination power between cases with cancers and donors." (PMID 36428760, 2022). "The pattern of cell fitness alterations associated with AGR2 and AGR3 extinction are highly correlated (r = 0.331, p = 4.58 × 10−21) and did not reveal any preferential vulnerability towards a given cancer type represented in the cell line panels of the CCLE." (PMID 35857928, 2022). "PDI family proteins, such as AGR2, PDI, PDIA3, PDIA4, and PDIA6 are reportedly upregulated in cancers, which are correlated with cancer progression and metastatic disease in pancreatic, kidney renal clear cell carcinoma (KIRC), ovarian cancers, glioblastoma and lung adenocarcinoma." (PMID 36202782, 2022). "When ranking the copy number values from highest to lowest values, there was no preferential contribution of the cancer types to presenting high or low AGR2/3 copy numbers." (PMID 35857928, 2022). "Therefore, the interpretation of our results requires caution, and it seems that AGR2 downregulation may act more strongly as a downstream effector of TGF-β in the focal adhesion pathway leading to an enhanced cascade of signaling events favoring cancer progression and dissemination." (PMID 36142758, 2022). "Recently, AGR2 was identified as a crucial component of the cellular machinery responsible for maintaining the epithelial phenotype, thereby interfering with the induction of mesenchymal phenotype cells by TGF-β effects in cancer." (PMID 36142758, 2022). "Therefore, using in silico analyses, we evaluated the expression of AGR2 and AGR3 mRNA in both the EOC cancer cell line encyclopedia (CCLE) and the EOC cancer genome atlas (TCGA) databases." (PMID 34452625, 2021). "However, the mechanism through which AGR2 expression is regulated, not only during EMT, but also in the early stages of cancer development, remains to be elucidated." (PMID 32570918, 2020). "This provides the first evidence of AGR2 localization on the external surface of cancer cells, rather than solely residing within the ER." (PMID 33005802, 2020). "Although the involvement and molecular function of AGR2 in tumorigenesis has been exponentially reported over the past decade, its regulation during cancer development and progression has not been completely elucidated." (PMID 32570918, 2020). "Earlier works indicated that intracellular AGR2 partnered with the Ly6/PLAUR domain-containing protein 3 (LYPD3), a protein involved in cell interactions with the extracellular matrix, the provision of cancer cell mobility and metastasis." (PMID 31247903, 2019). "AGR2 was not only significantly downregulated in type II EC as recently reported by others but also in grade III endometrioid compared to grade I and II cancers." (PMID 30140383, 2018). "When taken together, AGR2 secretion and cell surface localization are characteristics of cancer, whereas AGR2 expression alone is not." (PMID 30544619, 2018). "Anteriorgradient 2 secretion and cell surface localization are characteristics of cancer, whereas AGR2 expression alone is not." (PMID 30544619, 2018). "Differential subcellular localization of protein molecules shown by both AGR2 (cell interior to cell exterior) and CD10 (cell exterior to cell interior) could well be a property of cancer cells." (PMID 26894971, 2016). "Taken together, secretion and cell surface localization of AGR2 are characteristic of cancer, while expression of AGR2 by itself is not." (PMID 26894971, 2016). "To further confirm that AGR2 is essential for cancer tumorigenesis, we next investigated the effects of overexpressing AGR2 in non-tumorigenic HBECs using lentivirus-mediated infection with either empty vector (HBEC-EV) or AGR2 containing vector (HBEC-AGR2)." (PMID 27240165, 2016).
cancer (continued). "AGR2 expression also results in YAP1 activation and induced AREG expression in human cancer cells." (PMID 27764193, 2016). "The take home message is that differential subcellular localization or protein address of AGR2 – cell interior vs. cell exterior – not expression, makes AGR2 a cancer biomarker." (PMID 26894971, 2016). "The observation above suggested that AGR2 might play a key role in pro-survival, EMT, and self-renewal, which is a characteristic of cancer stem cells." (PMID 25871396, 2015). "AGR2 expression in SNU-869 enhanced cell proliferation rate that should result in the increased cell viability measured by the MTT assay as in normal mammary epithelial cells and in various cancer cells." (PMID 25367337, 2014). "We observed that three disulfide isomerases, AGR2, AGR3, and TXNDC5, are overexpressed in cancer." (PMID 25243088, 2014). "Although correlation of AGR2 expression with ER is further supported by estrogen-dependent induction of AGR2 expression, AGR2 expression is not restricted to ER-positive cancer cells." (PMID 25367337, 2014). "Anterior gradient homolog 2 (AGR2) is a functional protein with critical roles in a diverse range of biological systems, including vertebrate tissue development, inflammatory tissue injury responses, and cancer progression." (PMID 23029506, 2012). "The cancer cells (except LuCaP49) could be distinguished by their expression of any one of the cancer genes AMACR, PCA3, AGR2; their expression levels were variable." (PMID 21605402, 2011). "Indeed, AGR2 expression showed a negative correlation with SLFN11 expression in the Cancer Cell Line Encyclopedia dataset." (PMID 40459063, 2025). "The connection between AGR2 and EMT across various cancer types remains unclear." (PMID 39062458, 2024). "It is also not clear whether AGR2 secretion is a cancer cell-specific phenomenon or if it is also secreted from the limited number of normal tissues that express it under physiological conditions (e.g., colon)." (PMID 39727484, 2024). "For AGR2-negative stem-like cancer cells, factors like PENK that can target scTF could be effective in differentiation therapy." (PMID 38595814, 2024). "However, since AGR2 is not specific to breast, it cannot be used alone for early cancer detection as a serum biomarker, and needs to be integrated into the diagnostic score." (PMID 37197416, 2023). "However, the transcriptional regulation of AGR2 in the setting of cancer cell proliferation, migration, and invasion has not yet been fully elucidated." (PMID 36329620, 2023). "However, the relationship between AGR2 and TGF-β may be complex and context dependent, and further research is necessary to fully understand its implications for cancer progression and profibrotic changes." (PMID 37175601, 2023). "It is also important to note that four independent studies, and ours, on nine cancer cell lines of different origin in total, have identified GRP78/BiP/HSPA5, the ER residential chaperone and one of key central regulators of ER processes, to interact with AGR2." (PMID 34929376, 2022). "Furthermore, AGR2vH, a spliced variant of AGR2 lacking the C-terminal KTEL motif, dramatically promotes cancer cell migration and invasion in vitro." (PMID 33413231, 2021). "Therefore, antibodies raised against AGR2 would recognize specifically cancer cells and not AGR2-expressing normal cells." (PMID 34911496, 2021). "Interestingly, AGR2-207 that are not annotated to produce any functional proteins are notably expressed in cancers." (PMID 33005802, 2020). "Thus, identifying the AGR2/ miR-200c /ZEB1 axis and its involvement in cancer progression could represent a new strategy leading to more efficient targeting and/or preventing the development of metastasis." (PMID 32570918, 2020).
cancer (continued). "The ability of the intercellular AGR2 to enhance drug resistance is likely to be consequential to its ability to regulate the ERAD pathway, while expression of eAGR2 is likely to contribute to the resilience of cancer cells that are surviving in an inflammatory microenvironment." (PMID 31247903, 2019). "This research did not set out to quantify the percentage of cancer-secreted AGR2 that might be targeted by ɑ-AGR2." (PMID 31303962, 2019). "Trafficking of EGFR to the plasma membrane through AGR2-dependent catalysis in cancers might also be important for its' oncogenic function because AGR2-negative cells fail to localize EGFR to its membrane destination." (PMID 29339412, 2018). "AGR2 staining was strikingly positive in cancer and negative in normal." (PMID 30559929, 2018). "Noncancerous organs also express, but not secrete AGR2, while cancer cells secrete AGR2." (PMID 30544619, 2018). "To examine the induction of AGR2 expression in the early stages of PDAC development, we performed a detailed immunohistochemical analysis in human CP and in the tissue compartment adjacent to cancer, both characterized by the presence of pre-neoplastic lesions." (PMID 27941872, 2017). "Since PIMA is a particularly aggressive cancer subtype without specific therapeutic options, our findings suggest that pharmacological inhibition of either AGR2 or its upstream regulator, FOXM1, may be beneficial for PIMA patients." (PMID 29267283, 2017). "Urine from a cohort of 20 non-cancer (NB) and 20 cancer (CB) patients was tested for AGR2 by ELISA." (PMID 26894971, 2016). "In some organs like the prostate and pancreas, AGR2 is absent in normal epithelial cells and present in cancer cells, while in others like the bladder, AGR2 is present in normal urothelial cells but absent in cancer cells of a majority of tumors." (PMID 26445321, 2015). "Although mRNA and DNA copy numbers of AGR2 in HNSCC were not as significant as in other cancers." (PMID 25871396, 2015). "We did not observe AGR2 up-regulation in cancer cells vs. normal cells." (PMID 26445321, 2015). "Thus, as shown for other ER resident proteins, increased AGR2 expression in PTC could enhance ER folding capacity and allow cancer cells to cope with increased protein production and secretion." (PMID 24976026, 2014). "Furthermore, an anti-AGR2 therapy, unlike fulvestrant, can potentially function in cancers driven by cyclin D1 that can no longer respond to E2, given the ER-independent actions of AGR2 on cyclin D1." (PMID 20525379, 2010). "AGR2 provided no predictive value for recurrence for individuals with low stage cancer." (PMID 21144054, 2010). "Interestingly, the reduced AGR2 expression levels were not contributed to poor prognosis in many other cancers in TCGA datasets, suggesting that AGR2 may play a unique role in PCa." (PMID 37121942, 2023). "Therefore, based on recent findings demonstrating the contribution of AGR2 to the EMT and cancer progression, in addition to in silico analysis of AGR2 promoter predicting a binding site for ZEB1, we aimed to confirm regulatory effect of ZEB1 on the expression of AGR2." (PMID 32570918, 2020). "Here, we provide a review of the literature relating to the non-canonical PDIs ERp44, AGR2, and AGR3, which have been identified as strong dependencies in specific cancer subtypes according to the DepMap database." (PMID 40867591, 2025). "In all cancer types, AGR3 was expressed at a lower level than AGR2, and often not evaluable in samples from three cancer types: BLCA, HNSC and OVCA." (PMID 35857928, 2022). "These genes included AGR2, KRT17, SPDEF, and LAD1 which were expressed in EV-RNA of patients 5 and 15 and of all cancer cell lines, but not in HBDs." (PMID 33761899, 2021). "We showed by western blot that AGR2 protein was overexpressed in pancreatic CSC isolated from two primary patient-derived cell lines (A6L and 185) when compared to non-stem cancer cells." (PMID 27941872, 2017).
cancer (continued). "In human cancer cell lines, EGFR signaling is not possible without AGR2’s presence." (PMID 27764193, 2016). "Moreover, the overexpression of AGR2 and AGR3 may be a prognosis factor for survival, which could be favourable or not favourable depending on the cancer type." (PMID 35857928, 2022).